CBS (cystathionine beta-synthase)
Diseases named in the same sentence as CBS in open-access papers (continued):
Sharing a sentence is not in itself a finding about the gene and the disease.
hyperlipidemia (4 papers, 2018 to 2021). "In conclusion, CBS-KO rabbits have impaired growth and metabolism, although it remains to elucidated whether these changes are the direct effect of the mutation, or an indirect effect of hyperlipidemia or high homocysteine." (PMID 33054837, 2020). "The results obtained from hyperlipidemia patients and the CBS KO and CSE KO mice suggest that the disulfide bonds of HSA undergo S-thiolation with increasing concentration of the disulfide molecules in serum." (PMID 29343798, 2018). "It is striking to note that most of the S-thiolated cysteine residues detected in the serum albumins from the hyperlipidemia patients, CBS KO and CSE KO mice, and in the rHSA treated with homocystine or cystine in vitro were located in subdomain A." (PMID 29343798, 2018). "Our data suggest that hyperlipidemia and the related oxidative stress significantly reduced H2S production and CSE and CBS expression in vivo and in vitro." (PMID 32215177, 2020). "As evidenced by the significant decrease in expression of CSE and CBS in the penile tissue of the HFD rats as compared to NC rats, hyperlipidemia inhibited the expression of these two H2S synthetic enzymes (P < 0.05)." (PMID 32215177, 2020). "Since hyperlipidemia results in oxidative stress, to further clarify the role of oxidative stress in H2S formation, the expression of CSE and CBS and H2S levels in CSMC under oxidative stress were determined." (PMID 32215177, 2020). "In addition, we provide the first molecular evidence that hyperlipidemia and H2O2 induces oxidative stress, and this occurs alongside a reduction of H2S production and CSE and CBS expression in vivo or in vitro, which was attenuated by STS treatment, suggesting an antioxidative role of STS." (PMID 32215177, 2020). "Serine could condense with Hcy to synthesize Cys and thus alleviate oxidative stress via supporting GSH synthesis, and the decrease in CBS and CSE activities in rats with HFD-induced hyperlipidemia caused the upstream accumulation of Hcy and the lack of downstream GSH." (PMID 34336118, 2021). "Nevertheless, 3-MST expression did not change in penile tissues from rats with hyperlipidemia, indicating the downregulation of CSE and CBS might contribute to the decreased H2S production in the rats with hyperlipidemia." (PMID 32215177, 2020).
ischemia (4 papers, 2014 to 2020). A hypoperfusion of the BLOOD through an organ or tissue caused by a PATHOLOGIC CONSTRICTION or obstruction of its BLOOD VESSELS, or an absence of BLOOD CIRCULATION. "Therefore, it appears that increased CBS expression and activation may underlie the increased production of H2S in ischemia." (PMID 25873304, 2015). "However, given the efficacy of AOAA in diminishing cysteine-induced infarct volume, it necessitates further investigation into CBS and its role in ischemia." (PMID 33212887, 2020). "Meanwhile, in ischemia myocardium, three H2S-producing enzymes, cystathionine γ-lyase (CSE), cystathionine-β-synthase (CBS), and 3-mercaptopyruvate sulfurtransferase (3-MST) significantly increased." (PMID 27057284, 2016). "Results obtained from this study indicated that the expression of both CBS and CSE was reduced in the kidney subjected to 45‐min ischemia followed by 24‐h reperfusion." (PMID 25539831, 2014). "The aim of this study was to investigate the effect of downregulation of CBS and CSE expression on endogenous H2S and glutathione production and its impact on kidney inflammatory response during ischemia followed by a longer period of reperfusion (24 h) injury." (PMID 25539831, 2014).
acute pancreatitis (3 papers, 2012 to 2025). An acute inflammatory process that leads to necrosis of the pancreatic parenchyma. "In conclusion, we found that VB 12 protected acute pancreatitis associated with oxidative stress via CBS/SIRT1 pathway." (PMID 34925701, 2021). "More recently, we have shown an important role of CBS in the pathogenesis of acute pancreatitis and associated lung injury." (PMID 24278674, 2012). "To explore the role of CBS in acute pancreatitis, we constructed a classic AP model induced by sodium taurocholate (NaT)." (PMID 34925701, 2021). "In conditions that can present more acutely (Cases 4–6), there is also a superimposed risk of metabolic decompensation (vascular events in CBS deficiency, potentially lethal metabolic encephalopathy in MSUD, acute pancreatitis in genetic hypertriglyceridemias)." (PMID 40376563, 2025). "Our study provides basic evidence that targeting CBS/SIRT1 pathway might be a therapeutic strategy for acute pancreatitis." (PMID 34925701, 2021). "In the current study, the aims of this study were to determine (I) whether VB 12 attenuates the pathological damage of acute pancreatitis by CBS and (II) whether VB 12 inhibited oxidative stress and remedy mitochondrial dysfunction in acinar cells via CBS/SIRT1 signaling." (PMID 34925701, 2021). "Therefore, CBS is a potential target of VB 12 in the treatment of acute pancreatitis." (PMID 34925701, 2021). "However, whether CBS is involved in the pathogenesis of acute pancreatitis remains unclear." (PMID 34925701, 2021). "Since both CBS and CSE, two major H2S forming enzymes, are highly expressed in pancreatic acinar cells, it is of interest to understand the potential role of H2S in acute pancreatitis." (PMID 24278674, 2012).
cardiac hypertrophy (3 papers, 2017 to 2019). "Our results support that CBS deficiency induces cardiac hypertrophy in mice." (PMID 28623294, 2017). "CBS+/− mice hearts showed increased protein expression of β-MHC providing further confirmation of cardiac hypertrophy in HHcy mice." (PMID 31178749, 2019). "CBS+/− mice sections showed fewer cells per uniform area measured indicating greater cell size and cardiac hypertrophy." (PMID 31178749, 2019). "The results showed that the down-regulation of H2S/CBS pathway induced by high-salt diet was closely correlated with myocardial hypertrophy." (PMID 28360857, 2017). "In the present study, we found that high-salt diet significantly reduced H2S content and CBS mRNA and protein expressions of myocardial tissues with significant myocardial hypertrophy in Dahl rats." (PMID 28360857, 2017). "H2S donor diet normalized all signs of cardiac hypertrophy in CBS+/− mice." (PMID 31178749, 2019). "We subsequently measured histological and molecular markers of cardiac hypertrophy in CBS+/− mice with and without SG1002 diet." (PMID 31178749, 2019). "In contrast, myocardial hypertrophy became obvious in SD rats treated with HA, an inhibitor of CBS, as compared with SD + HS rats without HA treatment." (PMID 28360857, 2017). "Lack of CBS induces cardiac hypertrophy; plausibly via HHcy, that reduces anti-hypertrophic miR-133a." (PMID 28623294, 2017).
Cerebral edema (3 papers, 2017 to 2019). "Elevated methionine levels (> 1000 μmol/L) are a major concern in CBS-deficient patients, and cerebral oedema has previously been reported in these patients when treated with betaine anhydrous." (PMID 30871635, 2019). "For example, patients with CBS deficiency who were treated with betaine therapy showed cerebral edema." (PMID 29503817, 2018). "Cerebral edema has also been seen in a few non-CBS-deficient patients with high levels of Met." (PMID 27778219, 2017). "A number of other CBS deficient patients on betaine treatment have had Met levels above 1000 μmol/L and have not experienced cerebral edema." (PMID 27778219, 2017).
chronic kidney disease (3 papers, 2021 to 2026). Impairment of the renal function secondary to chronic kidney damage persisting for three or more months. "Cluster 2 captured the metabolic decline, with loss of Cystathionine beta‐synthase (CBS), a critical enzyme in sulfur amino acid metabolism and linked to oxidative stress and chronic kidney disease (CKD), and Sirt3, a regulator of mitochondrial ROS through Superoxide dismutase (SOD2)." (PMID 41508419, 2026). "However, a recent clinical study of chronic kidney disease patients revealed significantly lower plasma H2S and downregulation of CBS and CSE genes in blood mononuclear cells of these patients, which positively correlated with reduced GFR and disease severity relative to healthy control group." (PMID 39796237, 2025). "A rat model of chronic kidney disease (CKD) downregulates CGL, CBS, and the subsequent H2S production in liver and kidney." (PMID 33675469, 2021).
classic homocystinuria (3 papers, 2021 to 2025). "Classic homocystinuria is an autosomal recessive disorder caused by mutations in CBS gene on chromosome 21q22.3 leading to deficient activity of CBS (OMIM 236200)." (PMID 34955754, 2021).
depression (3 papers, 2017 to 2025). "Our results showed that adult PTSD mice exhibited more pronounced decreases in H2S content and CBS expression in the hippocampus, which were associated with anxiety and depression-like behavior compared with adolescent PTSD mice." (PMID 40551819, 2025). "In the present study, we found that adult PTSD mice exhibited more pronounced decrease in H2S content and CBS expression in the hippocampus, which were associated with anxiety and depression-like behavior compared with adolescence PTSD mice." (PMID 40551819, 2025). "In this study, we examined the influence of CBS/H2S on anxiety and depression-like behavior following the inescapable foot shock (IFS) procedure during early adolescence (postnatal days 28-35) or adulthood (postnatal days 63-70)." (PMID 40551819, 2025). "Our previous results also showed that treatment with NaHS significantly attenuated the reduction of CBS expression in the mouse hippocampus in a CUMS-induced depression model." (PMID 28842592, 2017). "In other words, excitatory actions of the CBS-H2S signaling system attenuated the magnitude of the secondary hypoxic respiratory depression." (PMID 28713283, 2017). "Moreover, similar anxiety and depression-like behavior were observed in mice after injection of CBS antibodies into the hippocampus." (PMID 40551819, 2025). "In conclusion, CBS/H2S may ameliorate anxiety and depression-like behaviors by activating the CREB/BDNF signaling pathway in the hippocampus of mice exposed to IFS." (PMID 40551819, 2025).
diabetic retinopathy (3 papers, 2020 to 2022). "For instance, different studies have described that reduced expression of CSE or/and CBS favours the development/progression of diabetic retinopathy, cardiopathy, and nephropathy." (PMID 35453313, 2022). "Results presented here clearly demonstrate that donors with diabetic retinopathy have decreased levels of both CBS and MTHFR." (PMID 31938715, 2020). "Hypermethylated promoters of both CBS and MTHFR are found in the retinal microvasculature from human donors with diabetic retinopathy compared to the age-matched non diabetic donors, implying the role of DNA methylation in downregulation of CBS and MTHFR." (PMID 32961662, 2020). "Consistent with CBS, in the same diabetic retinopathy donors, gene transcripts of MTHFR and CSE also decreased by 40 and 60%, respectively." (PMID 31938715, 2020). "In the same retinal microvessel preparations from donors with diabetic retinopathy, DNA at the promoters of CBS and MTHFR were hypermethylated." (PMID 31938715, 2020). "The role of DNA methylation in the regulation of CBS and MTHFR gene transcripts in diabetic retinopathy was determined." (PMID 31938715, 2020). "Since CBS and CSE are also intimately involved in regulating H2S levels, as with the transsulfuration and remethylation machinery, diabetic retinopathy donors had over a 2-fold decrease in retinal H2S levels." (PMID 31938715, 2020). "The enzymes important for both transsulfuration and remethylation of homocysteine including CBS, CSE and MTHFR, were 40–60% lower in the retinal microvasculature from diabetic retinopathy donors." (PMID 31938715, 2020). "Homocysteine and H2S levels were analyzed in the retina, and CBS, CSE and MTHFR in the retinal microvasculature from human donors with established diabetic retinopathy." (PMID 31938715, 2020). "Compared to non-diabetic control donors, diabetic retinopathy donors had 40–60% reduction in the gene and protein expressions of CBS, and 60% decrease in CBS enzyme activity." (PMID 31938715, 2020).
hepatopathy (3 papers, 2016 to 2024). "A human CBS knock-in transgene in the endogenous mouse Cbs locus has also been generated, which shows elevations in plasma and tissue levels of homocysteine but shows mild hepatopathy and no hepatic steatosis or fibrosis in contrast to classical models of homcystinuria." (PMID 29503817, 2018).
intellectual deficiency (3 papers, 2005 to 2022). "The use of CBS inhibitors has recently been suggested as a potential therapeutic option to reduce intellectual disability severity in DS patients." (PMID 35743210, 2022). "Conversely, decreased CBS activity, as observed in homocystinuria (OMIM 236200), causes increased excretion of homocysteine in patients’ urine and intellectual disability (ID)." (PMID 35743210, 2022).
intracerebral hemorrhage (3 papers, 2020 to 2025). A cerebrovascular disorder characterized by bleeding into one or both cerebral hemispheres including the basal ganglia and the cerebral cortex. "Another study demonstrated that NaHS significantly increased the expression of CBS and production of endogenous H2S after intracerebral hemorrhage injury." (PMID 40551819, 2025). "Administration of high doses of taurine in rat models of intracerebral hemorrhage (ICH) has been demonstrated to ameliorate white matter injury and neuronal damage by suppressing inflammatory mediators, glial activation, and neutrophil infiltration while concurrently enhancing CBS expression." (PMID 38931326, 2024).
iron-overload (3 papers, 2018 to 2022). "The reduced iron usage induced by the suppression of erythropoiesis is a major cause of the systemic iron overload in CBS knockout (CBS−/−) mice." (PMID 31551410, 2019). "This iron-overload related phenotype was partially reversed by administration of CBS-overexpressing adenovirus into CBS mutant mice." (PMID 36358508, 2022). "Anemia and iron overload in the serum, liver, spleen, and heart were noticed in CBS-KO mice with a hemochromatosis-like phenotype." (PMID 36358508, 2022).
liver fibrosis (3 papers, 2015 to 2025). "Previous study showed that CBS-deficient mice (tHcy 205μM) develop liver fibrosis concomitant with an enhanced expression of Col I and TGF-β, suggesting Hcy-induced TGF-β expression is a mechanism for Col1α1 gene induction." (PMID 26192994, 2015). "In logistic regression analyses, lower gene expression of cystathionine beta-synthase (CBS) and phosphatidylethanolamine N-methyltransferase (PEMT) was associated with a higher risk of hepatic fibrosis." (PMID 41180856, 2025). "According to the validation of clinical specimens, CBS, CYP1A2, FOXA1, GSTZ1, WDR72 and UHMK1 were specifically expressed in patients with liver fibrosis or hepatocirrhosis." (PMID 38287425, 2024). "The mechanism of CBS, CYP1A2, FOXA1, GSTZ1, WDR72 and UHMK1 in the progression of liver fibrosis is still unclear." (PMID 38287425, 2024).
lung adenocarcinoma (3 papers, 2016 to 2024). A carcinoma that arises from the lung and is characterized by the presence of malignant glandular epithelial cells. "We compared human lung adenocarcinoma samples to matched adjacent normal lung tissue and detected significantly higher protein levels of all three known H2S-producing enzymes, namely, CBS, CSE and 3-MST." (PMID 27808278, 2016). "To test whether endogenous H2S production stimulates mtDNA repair in lung adenocarcinoma cells, we monitored the effect of inhibition of CBS/CSE on the integrity of mtDNA and nuclear DNA." (PMID 27808278, 2016). "Here we show that human lung adenocarcinoma tissue expresses high levels of hydrogen sulfide (H2S) producing enzymes, namely, cystathionine beta-synthase (CBS), cystathionine gamma lyase (CSE) and 3-mercaptopyruvate sulfurtransferase (3-MST), in comparison to adjacent lung tissue." (PMID 27808278, 2016). "Therefore, there is a great need to develop novel, more specific inhibitors for H2S-producing enzymes, particularly for CSE and CBS, in context of lung adenocarcinoma." (PMID 27808278, 2016). "Significantly higher protein levels of CBS, CSE, and 3-MST were detected in human lung adenocarcinoma samples compared to normal counterparts." (PMID 38250807, 2024). "A link between H2S production and mitochondrial DNA repair was proposed, and the inhibition of CBS and CSE by aminooxyacetic acid or siRNA-mediated depletion of CBS, CSE, or MST in the lung adenocarcinoma A549 cell line resulted in compromised integrity of mitochondrial DNA." (PMID 30838088, 2019). "Similarly, elevated expression of CBS, CSE, and 3-MST and H2S production were also reported in multiple lung adenocarcinoma cell lines (A549, H522 and H1944) compared to non-malignant lung epithelial cells (BEAS 2B)." (PMID 38250807, 2024).
ovarian tumor (3 papers, 2013 to 2019). "This study reports an important role of CBS in promoting ovarian tumor growth and maintaining drug resistant phenotype by controlling cellular redox behavior and regulating mitochondrial bioenergetics." (PMID 24236104, 2013). "We found expression of CBS to be common in the cytosol of primary ovarian tumors, particularly in serous carcinoma, the most common histologic variant." (PMID 24236104, 2013). "We further established the roles of both CBS and SREBPs in regulating ovarian tumor growth in vivo." (PMID 26452259, 2015). "We examined the role of CBS and SREBPs in ovarian tumor growth." (PMID 26452259, 2015).
progressive supranuclear palsy (3 papers, 2021 to 2024). A rare late-onset neurodegenerative disease characterized by supranuclear gaze palsy, postural instability, progressive rigidity, and mild dementia. "Second, clinical diagnostic criteria for PSP–Richardson's syndrome and amyloid‐negative CBS (here inferred as CBD) were used to select a clinical cohort with likely a 4R‐tauopathy as the underlying pathological diagnosis." (PMID 37171832, 2023).
serous ovarian cancer (3 papers, 2013 to 2022). "This is particularly relevant given our observations that CBS expression is common in primary serous ovarian cancer which are most commonly treated with platinum-based chemotherapy and for which platinum resistance is a major problem." (PMID 24236104, 2013). "We report here that the expression of cystathionine-beta-synthase (CBS), a sulfur metabolism enzyme, is common in primary serous ovarian carcinoma." (PMID 24236104, 2013).
thrombosis (3 papers, 2014 to 2025). "A study from Italy showed a mutation of CBS gene associated with FVL mutation causes severe deep vein thrombosis despite only mild elevation of the homocysteine level." (PMID 25516723, 2014). "In the present work we have used label-free mass spectrometry and the Ingenuity Pathway Analysis resources to interrogate plasma proteomes of thrombosis-resistant Cbs−/− mice and compared them with plasma proteomes of thrombosis-prone CBS−/− humans." (PMID 32612202, 2020). "In seven families in a consanguinous Israeli Arab population, 4/45 members were both homozygous for CBS and heterozygous for the FVL mutation, and all four developed deep vein thrombosis." (PMID 25516723, 2014).
acute lymphoblastic leukemia (2 papers, 2022 to 2024). Leukemia with an acute onset, characterized by the presence of lymphoblasts in the bone marrow and the peripheral blood. "It is also worth noting the higher CBS expression in acute lymphocytic leukemia compared to chronic leukemias." (PMID 39062461, 2024). "Similarly, MPST (p < 0.001, Log2FC = −1.098) and CBS (p < 0.001, Log2FC = −0.582) also exhibit higher expression levels in Acute Lymphoblastic Leukemia, whereas CTH expression is lower (p < 0.001, Log2FC = 0.644)." (PMID 39062461, 2024).